MT-TY (mitochondrially encoded tRNA-Tyr (UAU/C))
Synonyms: trnY; formerly MTTY
Gene: Mitochondrial transfer RNA gene on chromosome MT (5,826 to 5,891, reverse strand). Ensembl gene ENSG00000210144.
Gene Ontology:
Molecular function: triplet codon-amino acid adaptor activity
Biological process: translation
Gene-disease validity (ClinGen):
ClinGen rates the evidence that MT-TY causes each of these diseases.
mitochondrial disease (mitochondrial): Definitive.